OXCT1-AS1 (OXCT1 antisense RNA 1)
Synonyms: SARRAH; LOC102723752
Gene: Long non-coding RNA gene on chromosome 5 (41,868,320 to 41,880,210, forward strand). Ensembl gene ENSG00000248668.
Diseases named in the same sentence as OXCT1-AS1 in open-access papers:
OXCT1-AS1 is named in the same sentence as 1 disease in open-access papers, as found by Europe PMC text mining. Sharing a sentence is not in itself a finding about the gene and the disease. The quoted sentences say what the papers report.
glioma (1 paper, 2021). A benign or malignant brain and spinal cord tumor that arises from glial cells (astrocytes, oligodendrocytes, ependymal cells). "In this study, bioinformatics methods and competing endogenous RNA (ceRNA) network regulatory rules were used to identify GBM-related lncRNAs and revealed that OXCT1 antisense RNA 1 (OXCT1-AS1) is a potential therapeutic target for the treatment of glioma." (PMID 33832517, 2021).